TFEB (transcription factor EB)
Description:
Transcription factor that acts as a master regulator of lysosomal biogenesis, autophagy, lysosomal exocytosis, lipid catabolism, energy metabolism and immune response. Specifically recognizes and binds E-box sequences (5'-CANNTG-3'); efficient DNA-binding requires dimerization with itself or with another MiT/TFE family member such as TFE3 or MITF. Involved in the cellular response to amino acid availability by acting downstream of MTOR: in the presence of nutrients, TFEB phosphorylation by MTOR promotes its cytosolic retention and subsequent inactivation. Upon starvation or lysosomal stress, inhibition of MTOR induces TFEB dephosphorylation, resulting in nuclear localization and transcription factor activity. Specifically recognizes and binds the CLEAR-box sequence (5'-GTCACGTGAC-3') present in the regulatory region of many lysosomal genes, leading to activate their expression, thereby playing a central role in expression of lysosomal genes. Regulates lysosomal positioning in response to nutrient deprivation by promoting the expression of PIP4P1. Acts as a positive regulator of autophagy by promoting expression of genes involved in autophagy. In association with TFE3, activates the expression of CD40L in T-cells, thereby playing a role in T-cell-dependent antibody responses in activated CD4(+) T-cells and thymus-dependent humoral immunity (By similarity). Specifically recognizes the gamma-E3 box, a subset of E-boxes, present in the heavy-chain immunoglobulin enhancer. Plays a role in the signal transduction processes required for normal vascularization of the placenta (By similarity). Involved in the immune response to infection by the bacteria S.aureus, S.typhimurium or S.enterica: infection promotes itaconate production, leading to alkylation, resulting in nuclear localization and transcription factor activity. Itaconate-mediated alkylation activates TFEB-dependent lysosomal biogenesis, facilitating the bacteria clearance during the antibacterial innate immune response. In association with ACSS2, promotes the expression of genes involved in lysosome biogenesis and both autophagy upon glucose deprivation.
Synonyms: bHLHe35; TCFEB; ALPHATFEB
Tractability: Small molecule: a structure with a bound ligand is known. PROTAC: UniProt records ubiquitination sites on it; ubiquitination databases record sites on it; its protein half-life has been measured.
Target class: Transcription factor
Gene: Protein-coding gene on chromosome 6 (41,683,978 to 41,736,259, reverse strand). Ensembl gene ENSG00000112561.
Subcellular location: Nucleus; Cytoplasm, cytosol; Lysosome membrane
Subcellular location (Human Protein Atlas): Cytosol
Pathways (Reactome):
Circadian clock: Phosphorylated BMAL1:CLOCK (ARNTL:CLOCK) activates expression of core clock genes
Developmental Biology: Transcriptional and post-translational regulation of MITF-M expression and activity
Gene Ontology:
Molecular function: DNA-binding transcription factor activity; enzyme binding; protein binding; sequence-specific double-stranded DNA binding; transcription cis-regulatory region binding; DNA-binding transcription factor activity, RNA polymerase II-specific; RNA polymerase II cis-regulatory region sequence-specific DNA binding; DNA binding; DNA-binding transcription activator activity, RNA polymerase II-specific; protein dimerization activity; protein heterodimerization activity
Biological process: antibacterial innate immune response; cellular response to amino acid starvation; cellular response to starvation; lysosome localization; lysosome organization; positive regulation of autophagy; positive regulation of DNA-templated transcription; positive regulation of transcription by RNA polymerase II; regulation of lysosome organization; embryonic placenta development; humoral immune response; regulation of DNA-templated transcription; regulation of transcription by RNA polymerase II; defense response to Gram-negative bacterium
Cellular component: cytoplasm; cytosol; lysosomal membrane; nucleus; chromatin; transcription regulator complex
Genetic constraint (gnomAD): Loss-of-function variants: 12 observed, 41.66 expected, observed/expected ratio (o/e) 0.29, 90% interval 0.18 to 0.47. The upper end of that interval is the gene's LOEUF score, 0.47, which puts it in group 2 of 6, group 1 being the genes least tolerant of losing a copy. Missense variants: 509 observed, 601.18 expected, observed/expected ratio (o/e) 0.85, 90% interval 0.79 to 0.91. Synonymous variants: 244 observed, 248.95 expected, observed/expected ratio (o/e) 0.98, 90% interval 0.88 to 1.09.
Homologues: Orthologues: chimpanzee TFEB (99% identical), macaque TFEB (99% identical), pig TFEB (95% identical), chimpanzee TFEB (95% identical), rabbit TFEB (94% identical), rat Tfeb (94% identical), dog TFEB (94% identical), mouse Tfeb (93% identical), guinea pig TFEB (90% identical), tropical clawed frog tfeb (59% identical), zebrafish tfeb (57% identical), Drosophila melanogaster Mitf (35% identical), and 1 more. Paralogues in human: MITF (46% identical), TFE3 (45% identical), TFEC (30% identical).
Diseases named in the same sentence as TFEB in open-access papers:
TFEB is named in the same sentence as 288 diseases in open-access papers, as found by Europe PMC text mining. Sharing a sentence is not in itself a finding about the gene and the disease. The quoted sentences say what the papers report.
renal cell carcinoma (53 papers, 2007 to 2026). "Since TFEB amplification is associated with a more aggressive clinical manifestation and poor outcomes for renal cell carcinoma, efforts have been made to accurately diagnose patients with TFEB translocations for improved patient management." (PMID 38919532, 2024). "Researchers have shown that TFEB is overexpressed in renal cell cancer and is associated with aggressive biological behavior." (PMID 37885995, 2023). "PAX8 is a specific marker for distinguishing TFEB-associated renal cell carcinoma from epithelioid angiomyolipoma." (PMID 36550835, 2022). "TFEB-associated renal cell carcinoma is very rare and belongs to the microphthalmia — associated transcription family translocation renal cell carcinoma." (PMID 36550835, 2022). "TFEB amplification in renal cell carcinoma can occur independently of or in association with TFEB rearrangement." (PMID 31382581, 2019). "TFE-RCCs are a group of renal cell carcinomas caused by chromosomal translocations involving TFEB and TFE3 genes and representing around 2% of all RCCs, and almost 12% of papillary type II RCCs." (PMID 27668431, 2016). "TFE-fusion renal cell carcinomas (TFE-fusion RCCs) are caused by chromosomal translocations that lead to overexpression of the TFEB and TFE3 genes." (PMID 27668431, 2016). "Notably, plenty of other genes whose fusions are mainly linked to TFEB-rearranged renal cell carcinomas, such as NEAT1 and MALAT1, are involved in forming the speckle–paraspeckles complex." (PMID 39410016, 2024). "However, TFE3 gene breaks down at Xp11.2, and equilibrium translocations with ASPL, PSF, and other genes form new fusion genes, contributing to TFE3 or TFEB fusion gene formation and their high expression in vivo, thus causing renal cell carcinoma." (PMID 38261736, 2024). "Many studies have reported that TFEB-associated renal cell carcinoma has inert behavior." (PMID 36550835, 2022). "Indeed, cathepsin K is a recognized diagnostic tool for the identification of TFE3/TFEB-rearranged renal cell carcinoma, TFEB-amplified renal cell carcinoma, and pure epithelioid PEComa/epithelioid angiomyolipoma." (PMID 34069976, 2021). "Renal cell carcinomas (RCCs) driven by TFE3 rearrangement or TFEB alteration (MiT-RCC) account for up to 40% of pediatric RCCs but are rare in adults." (PMID 41899560, 2026). "For the first time, the molecular genetics of TFEB/6p21/VEGFA-amplified renal cell carcinoma were completely and systematically characterized by exon sequencing." (PMID 38730456, 2024). "Whole-exome molecular genetic analysis of TFEB/6p21/VEGFA-amplified renal cell carcinoma has enhanced our understanding of this type of tumor." (PMID 38730456, 2024). "The CNV results further suggested that the gain in chromosomes 1q, 2p, 4q, 6p, 16p, 17q, 18q, 19q, 22q and loss in chromosome 18q were consistent with previous findings in TFEB-amplified renal cell carcinoma." (PMID 38730456, 2024). "Such a finding is due to the presence of clusters of small cells or “pseudorosettes” giving various examples of these neoplasms a distinctive biphasic growth pattern, more commonly described in TFEB-rearranged renal cell carcinoma." (PMID 39410016, 2024). "The first case of TFEB/6p21/VEGFA-amplified renal cell carcinoma with genomic instability was reported, presenting a new outlook on the treatment and prognosis of this tumor." (PMID 38730456, 2024). "As per the recent WHO classification, TFE3 rearranged RCC and TFEB altered RCC are now considered as two separate molecularly defined renal cell carcinomas." (PMID 38265103, 2024). "In the 2022 WHO classification, TFEB-altered renal cell carcinomas became a separate entity that also includes RCCs with TFEB amplifications." (PMID 37999735, 2024).
renal cell carcinoma (continued). "Here, we report an example of TFEB-translocated renal cell carcinoma in a kidney transplant patient with the unusual event of distant metastasis in multiple organs, including the kidney transplant, which, to our knowledge, has not been reported before." (PMID 37415400, 2024). "A systematic review and differentiation of TFEB/6p21/VEGFA-amplified renal cell carcinoma and TFEB-translocated renal cell carcinoma in clinicopathological, histological, immunophenotypic, and molecular genetic features was performed." (PMID 38730456, 2024). "One of the entities included in this category is the TFEB-altered renal cell carcinoma, initially included in the 2016 WHO classification as a member of the microphthalmia (MiT/TFE) transcription factor family translocation carcinomas." (PMID 37415400, 2024). "Then, through immunohistochemical analysis and an extensive literature review, we differentiated the patient’s tumor from various types of renal cancer and diagnosed it as TFEB/6p21/VEGFA-amplified renal cell carcinoma." (PMID 38730456, 2024). "In contrast, TFEB is hyperactivated and plays a pathogenic role in some cancers, including Birt-Hogg-Dubé (BHD) syndrome, TFEB translocation renal cell carcinoma, and pancreatic cancer." (PMID 38365838, 2024). "TFEB/6p21/VEGFA-amplified renal cell carcinoma (RCC) is rare and difficult to diagnose, with diverse histological patterns and immunohistochemical and poorly defined molecular genetic characteristics." (PMID 38730456, 2024). "Translocations of the MiT family, particularly those involving the TFE3 and TFEB genes, have been well described in renal cell carcinoma." (PMID 38919532, 2024). "RCC with aberrant TFEB expression was a highly graded RCC, and TFEB-amplified renal cell carcinoma had a higher proportion of ≥ pT3 in TNM staging (p = 0.047)." (PMID 38730456, 2024). "Constitutive activation of MiT/TFE transcription factors, including TFEB, is identified to drive metabolic reprogramming in pancreatic cancer, and upregulation of TFEB can lead to tumorigenesis of renal cell carcinomas." (PMID 36184826, 2023). "The TFE3/TFEB rearrangement renal cell carcinoma is characterized by translocations involving the TFE3 and TFEB genes." (PMID 37367052, 2023). "The pathological features of twenty-seven TFE3-rearranged renal cell carcinomas and ten TFEB-rearranged renal cell carcinomas have already been reported." (PMID 35980471, 2022). "Cathepsin K and parvalbumin are the two useful markers in the differential diagnosis between oncocytoma and TFE3/TFEB-rearranged renal cell carcinoma." (PMID 35980471, 2022). "On the other hand, cathepsin K is positive in TFEB-rearranged renal cell carcinoma and half of TFE3-rearranged renal cell carcinoma while it is negative in clear cell renal cell carcinoma." (PMID 35980471, 2022). "Cathepsin K is positive in TFEB-rearranged renal cell carcinoma and half of TFE3-rearranged renal cell carcinoma while it is negative in chromophobe renal cell carcinoma." (PMID 35980471, 2022). "Of course, staining for CK7 favors papillary renal cell carcinoma, confirming its usefulness in distinguishing papillary renal cell carcinoma from TFE3 and TFEB-rearranged renal cell carcinomas." (PMID 35980471, 2022). "While AMACR is not useful in the differential diagnosis with TFE3-rearranged renal cell carcinomas, being positive in both tumors, such marker is usually under-expressed in TFEB-rearranged renal cell carcinomas." (PMID 35980471, 2022). "Parvalbumin and CK7/S100A1 respectively are of paramount importance when TFE3/TFEB-rearranged renal cell carcinoma resembles oncocytoma and chromophobe renal cell carcinoma." (PMID 35980471, 2022). "On the other hand, cathepsin K is positive in TFEB-rearranged renal cell carcinoma and half of TFE3-rearranged renal cell carcinoma while it is negative in papillary renal cell carcinoma." (PMID 35980471, 2022).
renal cell carcinoma (continued). "In general, TFE3 and TFEB-rearranged renal cell carcinomas ought to be considered in the differential diagnosis, especially in young patients, every time pathologists have to deal with a renal tumor showing unusual microscopic findings." (PMID 35980471, 2022). "When TFE3 and TFEB-rearranged renal cell carcinomas exhibit extensive eosinophilic features, they can mimic oncocytoma and the eosinophilic variant of chromophobe renal cell carcinoma." (PMID 35980471, 2022). "TFE3/TFEB-rearranged renal cell carcinomas are characterized by translocations involving TFE3 and TFEB genes." (PMID 35980471, 2022). "Nevertheless, only 3 of 10 (30%) TFEB-rearranged renal cell carcinomas were considered positive for AMACR when a 5% cutoff was used, while none of them showed positive staining in more than 10% of the cells." (PMID 35980471, 2022). "AMACR is not useful in the differential diagnosis between papillary renal cell carcinoma and TFE3-rearranged renal cell carcinoma since both tumors are usually labeled for this marker, but it helps distinguish from TFEB-rearranged renal cell carcinoma." (PMID 35980471, 2022). "The expression of Melan-A and HMB45 was significantly lower in TFE3-rearranged renal cell carcinoma compared with TFEB-rearranged renal cell carcinoma, even when a 5% cutoff was used (17% and 27% respectively)." (PMID 35980471, 2022). "Despite initially considered rare tumors, TFE3 and TFEB-rearranged renal cell carcinoma represent 1–4% of renal cell carcinomas diagnosed among adults." (PMID 35980471, 2022). "CD10 is not useful in the differential diagnosis between clear cell renal cell carcinoma and TFE3-rearranged renal cell carcinoma since both tumors are usually labeled for this marker, but it helps distinguish from TFEB-rearranged renal cell carcinoma." (PMID 35980471, 2022). "A panel of immunohistochemistry markers useful to distinguish TFE3/TFEB-rearranged renal cell carcinoma from other common renal cell neoplasms should include cathepsin K, CA9, CK7, and parvalbumin." (PMID 35980471, 2022). "TFE3 gene translocations, and less frequently TFEB, are detected in renal cell carcinoma, alveolar soft part sarcoma, and perivascular epithelioid cell neoplasm." (PMID 33981707, 2021). "Nevertheless, few cases of TFEB-rearranged renal cell carcinomas with concomitant TFEB amplification have been described." (PMID 34069976, 2021). "In TFEB-rearranged renal cell carcinoma, cathepsin K staining is confirmed to be reliable, with strong and diffuse immunolabelling in the neoplastic cells, regardless of the fusion partner gene, such as MALAT1, ACTB, and NEAT1." (PMID 34069976, 2021). "Translocation renal cell carcinomas comprise two different tumors molecularly characterized by specific gene translocations, namely TFE3-rearranged renal cell carcinoma, the most common subtype, and TFEB-rearranged renal cell carcinoma." (PMID 34069976, 2021). "PAX8 immunostaining and CD68 (PG-M1) negativity support the diagnosis of TFEB-rearranged renal cell carcinoma, whereas pure epithelioid PEComa/epithelioid angiomyolipoma has the opposite immunoreactivity, being negative for PAX8 and positive for CD68 (PG-M1)." (PMID 34069976, 2021). "TFEB expression in tumors with TFEB amplification is lower compared with TFEB-rearranged renal cell carcinomas." (PMID 34069976, 2021). "TFEB was originally described as being translocated in a juvenile subset of pediatric renal cell carcinoma; however, whole-genome sequencing reported that somatic mutations were sporadically found in many different cancers." (PMID 33252196, 2020). "Overexpression of TFEB was occurred for the patients with renal cell carcinoma, and it was confirmed to accelerate tumorigenesis by inducing various oncogenic signals." (PMID 31799198, 2019). "More recently, renal cell carcinomas with TFEB amplification have been described and appear to be associated with a poor outcome." (PMID 31382581, 2019).